IL10 (interleukin 10)
Diseases named in the same sentence as IL10 in open-access papers (continued):
Sharing a sentence is not in itself a finding about the gene and the disease.
neuropathy (continued). "Several studies have reported lower levels of IL-10 in the CSF of patients affected by neuropathy compared with healthy controls, and a negative correlation between IL-10 levels and their pain ratings." (PMID 41169500, 2025). "Patients with painful neuropathy had a two-fold increase in IL-2 and TNF, while patients with nonpainful neuropathy had significantly higher mRNA levels of IL-4 and IL-10." (PMID 21994811, 2010). "Additionally, inflammatory mediators have been shown to differentiate between painful- from painless-neuropathies of various etiologies, including elevated serum IL-2, TNF-α, and reduced anti-inflammatory IL-10; IL-6 and IL-10 sural nerve biopsy expression; and TNF-α in human Schwann cells." (PMID 31065863, 2019). "A recent study investigated mRNA levels of proinflammatory cytokines interleukin-2 (IL-2) and tumor necrosis factor-alpha (TNF) as well as anti-inflammatory cytokines IL-4 and IL-10 among patients with painful neuropathy, nonpainful neuropathy and control participants." (PMID 21994811, 2010). "The untreated group without neuropathy showed higher concentrations of TNF-α, Chitinase3, IL-6, and IL-10 than the other groups." (PMID 34640602, 2021). "Here, we report anatomically distinct protein profiles for IL‐10, IL‐1β, and MCP‐1 under conditions of neuropathy, which has not been widely examined." (PMID 32977358, 2020). "Interestingly, elevated spinal IL-10 is observed in Sac rats with a 32-Day allodynia, suggesting that during the early spinal response to peripheral injury, significant changes in IL-10 protein levels is not requisite for controlling the development of neuropathy from a minor injury." (PMID 30961664, 2019).
Splenomegaly (31 papers, 2008 to 2026). Abnormal increased size of the spleen. "As infection and splenomegaly is similar in IL-10 deficient and wildtype animals, cell numbers follow the same trends shown." (PMID 26646149, 2015). "The IL-10−/− mice treated with exogenous WT BregIL-33, and to a less extent IL-10−/−BregIL-33, were clearly prevented from developing splenomegaly, a clinical condition usually caused by the inflammatory responses concomitant with IBD development." (PMID 24491821, 2014). "The erythrocyte osmotic fragility, splenomegaly, iron metabolism, hematological analysis, reactive oxygens species, sulfhydryl group, and interleukin-10 levels were evaluated." (PMID 40014902, 2025). "We suggest that the reduction of splenomegaly and hepatomegaly shown in this study were possibly affected by this significant enhancement of IL-10." (PMID 39403730, 2024). "In our study, the extent of the spike-specific IL-10 response was significantly lower in patients with benign polyclonal lymphoproliferation, manifested as hepatomegaly, splenomegaly, and lymphadenopathy." (PMID 37243231, 2023). "Research indicated that IL10−/− mice experiencing spontaneous inflammation often develop splenomegaly." (PMID 37765299, 2023). "Changes in IL-10 levels after SARS-CoV-2 antigen stimulation were found to be significantly associated with lymphadenopathy, splenomegaly, and hepatomegaly." (PMID 37243231, 2023). "IL-10 blockade resulted in more pronounced SJIA characteristics such as weight loss, splenomegaly, thrombocytosis, and neutrophilia in CFA-challenged WT mice." (PMID 36964620, 2023). "Interestingly, these results revealed a strong correlation of increased IL-10 with different clinical and laboratory parameters, implying disease manifestations to be linked with the increased immunological markers as well as clinical-like body-mass-index, splenomegaly, and pancytopenia." (PMID 34351903, 2021). "In spite of the lack of colonic inflammation in the WT groups, however, splenomegaly was clearly evident in both IL-10−/− and WT mice after IL-33 treatment." (PMID 24491821, 2014). "For S. mansonipositive children, those presenting with substantial splenomegaly also had significantly higher levels of circulating IL-10 than those who presented with moderate splenomegaly." (PMID 19149774, 2009). "Levels of circulating IL-10 were significantly higher in children who had splenomegaly-only than in children who had hepatomegaly-only." (PMID 19149774, 2009). "Lyn kinase knock-out mice develop severe splenomegaly along with the increased secretion of IL-10." (PMID 34209841, 2021). "Interestingly, IL-10−/−,T-Hk2−/− mice developed spontaneous rectal prolapse at a significantly lower rate than IL-10−/− mice, though weight change and splenomegaly were similar between the two." (PMID 30140438, 2018). "Hence, the enhanced splenomegaly observed in TgAlbCre-IL10-/- mice might be due to a higher level of extramedullary erythropoiesis, a phenomenon which was reported before to cause splenomegaly in T. congolense infected animals." (PMID 32012211, 2020). "In another study, low levels of IL-10 and IFN-γ were correlated to splenomegaly in S. japonicum-infected patients, similar to our finding showing an enlarged spleen in SMDSS mice." (PMID 40332187, 2025). "Several clinical and laboratory features observed in this model are consistent with MAS, such as splenomegaly, hyperferritinemia, and hypercytokinemia including elevation of IFN-γ, IL-6, and IL-10." (PMID 36964620, 2023). "Pearson’s correlation analysis of gut bacteria showed that P. distasonis had a negative correlation with splenomegaly, and anti-dsDNA IgG2c levels in serum, but a positive correlation with the PPs derived IL-10 producing B cells." (PMID 40761803, 2025). "In addition, CVID patients have been shown to have a decreased frequency of naïve regulatory T cells, one of the major sources of IL-10, in CVID patients with splenomegaly." (PMID 37243231, 2023).
Splenomegaly (continued). "Therefore, Blimp-1-dependent IL-10 produced by CD4+ T cells acts on myeloid cells, including MZM, to impair parasite killing, but also acts to limit splenomegaly." (PMID 26765224, 2016). "Another striking feature of L. donovani-infected mice lacking Blimp-1 or IL-10 expression by T cells was dramatic splenomegaly." (PMID 26765224, 2016). "In the absence of IL-10 production by T cells, MZM were lost and this was associated with disrupted lymphocyte trafficking and splenomegaly." (PMID 26765224, 2016). "However, unlike in Lyn-/-IL-10-/- mice, there was no enhancement of splenomegaly, CD4+ T cell activation (as measured by CD69 expression), CD4 T cell naïve and effector memory frequencies, or myeloid expansion in Lyn-/-.Ighg3-cre.DTA and Lyn-/-.Ighg3-cre.IRF4f/f mice compared to Lyn-/- controls." (PMID 41445737, 2025). "In the absence of IL-10, establishment of MHV68 latency is decreased concurrent with an increase in serum IL-12 p70 and splenomegaly, demonstrating a role for IL-10 in both establishment of latency as well as immunosuppression." (PMID 18389062, 2008). "Interestingly, the splenomegaly was significantly lower in the absence of TNFR1 signaling and the levels of circulating IL-10 were also reduced in this group compared with wild type mice." (PMID 30123776, 2018). "Thus, in our case the absence of splenomegaly and reduction of parasite load in Lipo:LiChimera-immunized mice could be the effect of balanced IFN-γ to IL-10 production due to immunization." (PMID 37631952, 2023). "Interestingly and consistent with the ELISA data, the percentages of IL-10-producing CD4+ cells were not different between WT and Bam32-/- mice, although the absolute numbers were higher than those from WT mice, which could be due to higher splenomegaly during the late stage of infection." (PMID 25875604, 2015).
brain injury (30 papers, 2011 to 2026). Acute and chronic (see also brain INJURIES, CHRONIC) injuries to the brain, including the cerebral hemispheres, CEREBELLUM, and brain STEM. "IL-10 deficiency exacerbates damage, whereas its over-expression reduces infarct volumes after ischemic brain injury." (PMID 22028848, 2011). "After a single mild traumatic brain injury, interleukin-10, interleukin-13, interleukin-4 and tumour necrosis factor-alpha were elevated 3 days post-injury while interleukin-10 and tumour necrosis factor-alpha levels were elevated 14-days post-injury." (PMID 41675431, 2026). "Visser K demonstrated that as a result of inflammatory responses after mTBI, interleukin-6 was the most promising biomarker for clinical diagnosis of brain injury, while interleukin-10 was a potential candidate for CT scan triage." (PMID 40881786, 2025). "For example, natural killer (NK) cells were recruited to the brain by ischemic neurons and this exacerbates ischemic brain injury, while Treg cells appear to be beneficial by releasing anti-inflammatory cytokines, such as IL-10." (PMID 37679730, 2023). "Overexpressing IL-10 MSCs were found to increase autophagy and protect rats from neuronal damage induced by traumatic brain injury." (PMID 37726805, 2023). "It is well documented that the levels of IL-10 significantly augmented in the serum and CSF after traumatic brain injury (TBI)." (PMID 35432810, 2021). "Inflammatory cytokines (IL-6, IL-10, and TNFα) were measured acutely in blood samples within 8 h following a medically diagnosed concussion and then 24 h later." (PMID 32450801, 2020). "In rats, IL-10 has been shown to have a protective effect on neurons after LPS treatment but also after brain injuries." (PMID 32717860, 2020). "Consistently, FN attenuated neuroinflammatory reaction through downregulating TNF-α and IL-1β and upregulating IL-10 in a rat model of traumatic brain injury." (PMID 31561418, 2019). "Specifically, an increase in the expression of IL-10 was inversely correlated with the expression of TNF-α, the latter of which has been directly implicated in neutrophil recruitment following diverse brain injury." (PMID 28529954, 2017). "Preclinical studies have shown that IL-10 reduces neuroinflammation following brain trauma and, in general, IL-10 treatment improves neurological outcomes after TBI." (PMID 28659854, 2017). "The present study revealed that the expression of IL-10 in the serum was significantly increased in response to ischemic brain injury, while it was markedly decreased by GLGZD treatment." (PMID 25815894, 2015). "The main cytokines associated with inflammation in ischemic brain injury are IL-1, TNF-α, IL-6, IL-10 and TGF-β and have been observed to be upregulated in ischemic brain injury." (PMID 25815894, 2015). "Although there is growing evidence that the role of IL-10 in neurons is to induce anti-apoptotic effects during neurodegenerative diseases and brain injuries, little if any attention has been given to the potential regulatory role of IL-10 in neuronal functions that regulate fertility." (PMID 30406179, 2018). "Given the intriguing multifactorial role of IL-10 in the resolution of inflammatory cascades that are important for promoting neurologic recovery from acute brain injury, here we present a comprehensive literature review of preclinical and clinical studies in this area." (PMID 28659854, 2017). "Lack of anti-inflammatory response at P1 might deprive the challenged brain of neurotrophic factors - such as TGF-β1, IL-10, IL-1ra and IL-6 - involved in neuronal survival and brain tissue repair following brain injuries." (PMID 21599903, 2011). "Our observations implying that IL-10 is a central mediator of the anti-inflammatory properties of EVs in the myocardium are consistent with previous studies suggesting that IL-10-overexpressing MSCs increased autophagy and protected rats against traumatic brain injury-induced neuronal damage." (PMID 36203611, 2022).
brain injury (continued). "Alternatively, M2 microglia facilitate recovery via promoting the release of anti-inflammatory cytokines, such as IL-10 and TGF-β after brain injury." (PMID 35409364, 2022). "In the traumatic brain injury model, HBOT augmented the production of immunosuppressive IL-10 to promote the effects of anti-inflammation." (PMID 34440146, 2021). "Although we did not examine IL10 production by these Bregs, there has been a recent study reporting a decline in IL10 producing B cells in brain injury patients." (PMID 29976949, 2018). "Previous experimental studies have shown that brain trauma initiates a cascade of multiple anti- and proinflammatory pathways with permeability-increasing properties, such as release of various cytokines such as IL6, TNF alpha, and IL10." (PMID 27822741, 2017). "In coherence with previous literature, in our study Il-6, IL-1ra, Il-8, IL-10, IL-15, MCP-1, MIP-1β, and IP10 were selected in the first two components of PCA as strong predictors of outcome confirming their role in the pathophysiology of brain injury." (PMID 27324502, 2016). "Inflammatory mediators, including IL-1β, IL-6, IL-10, TNF-α and NF-κB were assessed to examine whether GLGZD was involved in the inflammatory response in ischemic brain injury." (PMID 25815894, 2015).
cerebral infarction (30 papers, 2012 to 2025). An ischemic condition of the brain, producing a persistent focal neurological deficit in the area of distribution of the cerebral arteries. "In IS, IL-10 rs1800896 polymorphism was significantly associated with individual susceptibility to IS, especially for cerebral infarction." (PMID 34685473, 2021). "Subgroup analysis by ethnicity showed that polymorphisms of IL-6 −174G/C and IL-10 −1082A/G were significantly associated with cerebral infarction risk in Asians." (PMID 27679860, 2016). "The lower serum IL-10 concentration was significantly associated with an increased likelihood of cerebral infarction." (PMID 27679860, 2016). "Subgroup analysis by ethnicity showed that IL-6 −174G/C polymorphism (under all the five models) and IL-10 −1082A/G polymorphism (under the allelic model and heterologous model) were significantly associated with increased the cerebral infarction risk in Asians." (PMID 27679860, 2016). "Histopathological analysis and measurement of brain infarct size were performed, and cerebral levels of IL-6, IL-10, TNF-α, ICAM-1, NF-κB p65, and total antioxidant capacity were assessed." (PMID 38313176, 2023). "The IL-12 and TNF-α level were significantly decreased while IL-10 were significantly increased in cerebral infarction tissues in CsA@HFn treated MCAO mice." (PMID 35658867, 2022). "The level of IL-12, TNF-α and IL-10 in cerebral infarction tissues was also determined by ELISA method." (PMID 35658867, 2022). "ELISA results showed that as compared with normal saline, CsA@HFn significantly decreased the levels of IL-12 and TNF-α and increased the level of IL-10 in cerebral infarction tissue of MCAO mice." (PMID 35658867, 2022). "In human postmortem brain tissue samples, IL-10, IL-4, and their receptors co-localize with reactive astrocytes in active demyelinating MS lesions, as well as in areas of brain infarction." (PMID 36231129, 2022). "Brain infarct volume, neurobehavioral tests, microglia activation, IL-10 and IL-10R levels were further assessed for up to 14 days." (PMID 33532127, 2021). "In an animal model, both intraventricularly and systemically administered IL-10 have been shown to reduce cerebral infarction volume, and IL-10 has been suggested to be neuroprotective." (PMID 25923658, 2015). "MSCs transplanted into the brains of cerebral infarction model rats have been reported to affect cytokine release by up-regulating IL-10 and down-regulating TNF-α." (PMID 23049854, 2012). "In addition to brain infarct volume and histopathological assessment, the brain tissues were harvested to evaluate cerebral IL-6, IL-10, TNF-α, ICAM-1, NF-κB p65, and total antioxidant capacity levels." (PMID 36567842, 2022). "In TBI models, IL-10 not only attenuates neuroinflammation by reducing inflammatory cytokine production, but also was found be neuroprotective by increasing cerebral blood flow and reducing brain infarction." (PMID 33183330, 2020). "A recent study also documented that the CNS protection provided by IL-33 is primarily due to its ability to induce IL-10 production in microglia, whereas genetic deletion of ST2 expanded cerebral infarction by switching microglia toward an M1-like phenotype." (PMID 35269441, 2022). "Cerebral levels of IL-6, IL-10, TNF-α, NF-κB p65, and ICAM-1, besides cerebral infarct volume, were significantly elevated in control and vehicle related to sham groups, while total antioxidant capacity was markedly reduced." (PMID 36567842, 2022). "Neurons co-cultured with IL-10 KO glial cells have been found to be more sensitive to damage induced by NMDA or OGD and cerebral infarction volume in IL-10 KO mice is larger than that of the wild type in focal cerebral ischemia." (PMID 26366999, 2015).